MIR99AHG (mir-99a-let-7c cluster host gene)
Synonyms: MONC; DILA1; C21orf34; C21orf35; LINC00478; formerly FLJ38295
Gene: Long non-coding RNA gene on chromosome 21 (15,928,296 to 16,646,364, forward strand). Ensembl gene ENSG00000215386.
Gene Ontology:
Biological process: miRNA-mediated post-transcriptional gene silencing
Cellular component: RISC complex
Diseases named in the same sentence as MIR99AHG in open-access papers:
MIR99AHG is named in the same sentence as 27 diseases in open-access papers, as found by Europe PMC text mining. Sharing a sentence is not in itself a finding about the gene and the disease. The quoted sentences say what the papers report.
breast carcinoma (14 papers, 2016 to 2025). "Some studies found that down-regulation of MIR99AHG was associated with lung adenocarcinoma, colorectal cancer, pancreatic cancer and breast cancer 22, 29-32." (PMID 38495494, 2024). "Previous studies have reported that MIR99AHG, also known as MONK, is a good prognostic indicator of breast cancer, lung squamous cell carcinoma, and colorectal cancer." (PMID 31620361, 2019).
lung adenocarcinoma (11 papers, 2021 to 2025). A carcinoma that arises from the lung and is characterized by the presence of malignant glandular epithelial cells. "Interestingly, MIR99AHG was described recently as a tumor suppressor gene in lung adenocarcinoma and was associated with advanced tumor progression and poorer prognosis in gastric cancer." (PMID 35806468, 2022). "Apart from that, the MIR99AHG/miR‐218‐5p/GPM6A axis has a twofold lung cancer inhibitory effect in lung adenocarcinoma through the non‐coding tumor suppressor gene MIR99AHG." (PMID 39957375, 2025). "In this study, we aim to investigate the clinical significance of MIR99AHG expression in lung adenocarcinoma (LUAD), and its biological roles in LUAD progression." (PMID 36138468, 2022). "MIR99AHG is a potential noncoding tumor suppressor gene in lung adenocarcinoma." (PMID 35512135, 2022). "In a recently published article MIR99AHG was downregulated in lung adenocarcinoma tissues." (PMID 35895506, 2022). "In addition, the second tumor suppressor MIR99AHG/miR-218-5p/GPM6A axis provides two-fold lung cancer inhibition via non-coding tumor suppressor gene MIR99AHG in lung adenocarcinoma and miR-218-5p affects lung adenocarcinoma progression." (PMID 36289596, 2022). "By integrated bioinformatics analyses of differentially expressed long noncoding RNAs (lncRNAs) and arm-level CNVs in lung adenocarcinoma (LUAD), we identified a potential antitumor gene, MIR99AHG, encoding lncRNA MIR99AHG as well as a miR-99a/let-7c/miR-125b2 cluster on chromosome 21q." (PMID 33931593, 2021). "It is interesting to note that the lncRNA MIR99AHG could promote autophagy by binding to ANXA2, then generate miR-99a to suppress the expression of mTOR, postponing lung adenocarcinoma progression." (PMID 35158722, 2022).
acute megakaryoblastic leukemia (6 papers, 2018 to 2022). Acute megakaryoblastic leukemia (AMKL) is a form of acute myeloid leukemia (AML) that occurs predominantly in childhood and particularly in children with Down syndrome (DS-AMKL). "The knockdown of MIR99AHG by shRNAs in acute megakaryoblastic leukemia (AMKL) cell lines reduced leukemic growth." (PMID 35895506, 2022). "Moreover, MIR99AHG served as an oncogene in acute megakaryoblastic leukemia." (PMID 35806468, 2022). "MIR99AHG (also known as MONK), for example, highly expresses in acute megakaryocytic leukemia (AMKL) cell lines, and MONK knockout impacts the proliferation of leukemia cell lines and inhibits the growth of AMKL cancer samples." (PMID 35361740, 2022).
gastric cancer (6 papers, 2020 to 2022). A primary or metastatic malignant neoplasm involving the stomach. "Moreover, it is reported that MIR99AHG expression is up-regulated in gastric cancer, which is associated with clinical progression and poor prognosis of gastric cancer." (PMID 35361740, 2022). "Our data that MIR99AHG might be useful as a diagnostic and prognostic biomarker as well as a therapeutic target for gastric cancer in the future." (PMID 32874129, 2020). "MIR99AHG has been deeply investigated in gastric cancer and the results disclose the oncogenic role of MIR99AHG in gastric cancer." (PMID 34911544, 2021). "LncRNA MIR99AHG has been reported to be upregulated in acute myeloid leukemia (AML); however, its function in gastric cancer (GC) is still not clear." (PMID 32874129, 2020).
leukemia (4 papers, 2016 to 2022). A malignant (clonal) hematologic disorder, involving hematopoietic stem cells and characterized by the presence of primitive or atypical myeloid or lymphoid cells in the bone marrow and the blood. "Although MIR99AHG was shown to play an important role in leukaemia, little is known about its regulation." (PMID 27340920, 2016).
lung carcinoma (3 papers, 2022 to 2025). "For example, MIR99AHG, as a tumour progression-inhibiting factor, can delay lung cancer progression by synergistically promoting autophagy in lung cancer." (PMID 36844873, 2023).
lymph node metastasis (3 papers, 2020 to 2021). "The results showed that expression of MIR99AHG was positively associated to TNM stage and lymph node metastasis." (PMID 32874129, 2020).
pulmonary fibrosis (2 papers, 2022 to 2023). Chronic progressive interstitial lung disorder characterized by the replacement of the lung tissue by connective tissue, leading to progressive dyspnea, respiratory failure, or right heart failure. "Our data provide new insights into the role of MIR99AHG in regulating the formation of pulmonary fibrosis." (PMID 36138468, 2022). "Our findings suggest that MIR99AHG plays a key role in the progression of pulmonary fibrosis and is a potentially effective target for pulmonary fibrosis therapy." (PMID 36138468, 2022). "Altogether, our results suggest that MIR99AHG can inhibit the progression of pulmonary fibrosis in vivo." (PMID 36138468, 2022). "This study showed that downregulated MIR99AHG leads to the development of pulmonary fibrosis." (PMID 36138468, 2022). "In this study, we hypothesized that MIR99AHG plays an important role in pulmonary fibrosis based on the previous findings." (PMID 36138468, 2022). "Our findings suggest that MIR99AHG is a potential EMT inducer and could serve as a therapeutic target for pulmonary fibrosis." (PMID 36138468, 2022).
head and neck squamous cell carcinoma (1 paper, 2021). A squamous cell carcinoma that arises from any of the following anatomic sites: lip and oral cavity, nasal cavity, paranasal sinuses, pharynx, larynx, and salivary glands. "LncRNA MONC, mir-99a-let-7c cluster host gene, also known as MIR99AHG, is a good prognostic indicator of head and neck squamous cell carcinoma, lung squamous cell carcinoma, and colorectal cancer." (PMID 34193130, 2021).
vulvar squamous cell carcinoma (1 paper, 2020). An invasive squamous cell carcinoma arising from the vulva. "For instance, in vulvar squamous cell carcinoma, MIR99AHG and MIR31HG expressions are correlated and associated with tumor differentiation." (PMID 32079618, 2020).
tumor (15 papers, 2017 to 2024). "The results showed that NOTCH2 overexpression could recover the decreased tumor volume and weight caused by MIR99AHG inhibition." (PMID 34911544, 2021). "A previous study reported that MIR99AHG was significantly overexpressed in human GC tissues and can promote tumor progression." (PMID 37310469, 2023). "The expression of MIR99AHG in tumor tissues was examined by RT-qPCR, which showed that MIR99AHG remained stably overexpressed in nude mice." (PMID 36138468, 2022). "In the present study, we found that lncRNA MIR99AHG expression was downregulation in LUAD compared to the corresponding non-tumor tissues." (PMID 36138468, 2022). "The FISH assay confirmed the downregulation of MIR99AHG in LUAD tissues compared to the paired non-tumor samples, mainly located in the cytoplasm." (PMID 36138468, 2022). "All these suggest that MIR99AHG is a potential tumor biomarker that can be used for prognostic assessment and to guide targeted therapy." (PMID 35361740, 2022). "Overexpression of MIR99AHG has been reported to increase the expression of the miR-99a/let-7c/miR-125b2 cluster, synergistically acting as a tumor suppressor gene." (PMID 36138468, 2022). "Altogether, MIR99AHG served as a tumor suppressor gene mainly through the synergistic biological function of MIR99AHG and miR-99a." (PMID 33931593, 2021). "In summary, MIR99AHG emerges as a noncoding tumor suppressor gene in LUAD, providing a new strategy for antitumor therapy." (PMID 33931593, 2021). "Expression levels of MIR99AHG in tumor tissues were remarkably higher than that in adjacent tissues." (PMID 32874129, 2020). "Although a few studies described MIR99AHG as a tumor suppressor and promoter, the roles of MIR99AHG have remained largely unknown." (PMID 38976685, 2024). "In summary, MIR99AHG may function as a potential tumor suppressor and is positively correlated with survival in LUAD." (PMID 33931593, 2021). "Therefore, we speculated that MIR99AHG may act as a ceRNA of tumour-miR-25-3p to regulate target genes, thus playing critical roles in the progression of CHOL." (PMID 36158120, 2022). "Furthermore, due to the CND of MIR99AHG gene in LUAD, the loss of autophagy induced by MIR99AHG/miR-99a might promote the tumor initiation." (PMID 33931593, 2021). "Using the same rationale, we selected three regulatory axes for tumor suppression; these axes are designated as ANXA2P1/miR-20b-5p/FAM241A (C4orf32), MIR99AHG/miR-218-5p/GPM6A, and SH3RF3-AS1/miR-34a-5p/HECW2." (PMID 36289596, 2022).
cancer (12 papers, 2016 to 2025). A tumor composed of atypical neoplastic, often pleomorphic cells that invade other tissues. "In the TCGA database, MIR99AHG expression was associated with overall survival, with a difference in expression between cancer and adjacent tissues." (PMID 31620361, 2019). "Dysregulation of MIR99AHG is correlated with unfavorable survival times in patients with various cancer types." (PMID 36158120, 2022). "MIR99AHG was strongly up-regulated in human GC and contributed to cancer progression." (PMID 32874129, 2020).
infection (1 paper, 2022). The state of being infected such as from the introduction of a foreign agent such as serum, vaccine, antigenic substance or organism. "To examine the functional role of MIR99AHG during Mtb HN878 infection, we inhibited MIR99AHG using ASOs and analyzed its effect on the intracellular growth of Mtb in macrophages by CFU assays." (PMID 35895506, 2022). "In contrast, Mtb HN878 infection repressed MIR99AHG expression in a time dependent manner." (PMID 35895506, 2022). "Similarly, to Mtb HN878, H37Rv and H37Ra infection resulted in the downregulation of MIR99AHG mRNA expression at 4 h postinfection." (PMID 35895506, 2022). "We also identified a 73% reduction of MIR99AHG expression at 24 h post IL-4/IL-13 stimulation and a 69% reduction at 4 h post Mtb HN878 infection." (PMID 35895506, 2022). "MIR99AHG was downregulated by Mtb HN878, Mtb H37Rv, and Mtb H37Ra infection but upregulated in M. bovis BCG infected macrophages." (PMID 35895506, 2022). "Knockdown of MIR99AHG by ASOs significantly reduced the intracellular Mtb growth in IL-4/IL-13 stimulated macrophages at 72 h post Mtb HN878 infection but did not change the phagocytic ability of macrophages to uptake Mtb at 4 h postinfection." (PMID 35895506, 2022). "Altogether, these data show that MIR99AHG expression varies according to the macrophage polarization state; in IL-4/IL-13 polarized macrophages MIR99AHG expression was induced, while the expression of MIR99AHG was downregulated following Mtb HN878 infection and in active TB patients." (PMID 35895506, 2022).
MIR99AHG also shares sentences with these, for which no sentence is quoted: acute myeloid leukemia (2 papers); bladder cancer (2); colorectal cancer (2); prostate carcinoma (2); infarction (1); liver cancer (1); lung squamous cell carcinoma (1); megakaryoblastic leukemia (1); melanoma (1); metastatic melanoma (1); myeloid leukemia (1); oral squamous cell carcinoma (1); pancreatic cancer (1); skin melanoma (1).